IDH1 (isocitrate dehydrogenase (NADP(+)) 1)
Diseases named in the same sentence as IDH1 in open-access papers (continued):
Sharing a sentence is not in itself a finding about the gene and the disease.
glioblastoma (continued). "IDH1 mutants, such as R132H found in glioblastomas and other types of human cancers, have a neomorphic activity that uses NADPH to reduce αKG to 2-hydroxyglutarate (2HG)." (PMID 40943163, 2025). "An intraoperative pathology exam demonstrated a high-grade malignant neoplasm with necrosis, and the final pathology was found to be glioblastoma, isocitrate dehydrogenase 1 (IDH-1) (R132H)-wildtype, central nervous system (CNS) WHO Grade IV." (PMID 41356860, 2025). "In glioblastoma, the expression of wild-type IDH1 is increased about four times relative to healthy brain tissue." (PMID 41008904, 2025). "The mutual exclusivity of IDH1 and EGFR mutations suggests divergent oncogenic pathways, with IDH1 mutations predominantly associated with LGGs and EGFR mutations linked to more aggressive glioblastomas." (PMID 41425851, 2025). "We initially confirmed glioblastoma (GBM) malignancy and therapeutic responses to CCK overexpression and IDH1 mutations in cerebral cortex and frontal cortex tissue samples." (PMID 41057875, 2025). "Several prognostic features were characterized, including NF1 alteration and 21q loss in glioblastoma, and EGFR amplification and 22q loss in IDH1/2-mutant astrocytoma." (PMID 39164213, 2025). "These tests analyze tumor DNA and RNA to identify key genetic alterations, such as mutations in the IDH1 and IDH2 genes, MGMT promoter methylation, and EGFR amplification, which are pivotal in glioblastoma classification and prognosis." (PMID 39338377, 2024). "Non-EGFRvIII samples exhibited increased expression of S100A1, a marker of mesenchymal glioblastoma, whereas EGFRvIII samples exhibited higher expression of the classic/proneural subtype marker NOTCH1 and the proneural-associated gene IDH1." (PMID 38665799, 2024). "IDH1-wt glioblastoma typically displays distinct molecular features that contribute to its aggressive nature." (PMID 38646145, 2024). "Other groups, moreover, demonstrated the possibility of predicting the mutation of IDH1 and PTEN and the methylation of MGMT using radiological data, proposing a probabilistic neuroradiological atlas of different phenotypic glioblastomas." (PMID 39513861, 2024). "Traditionally, the surgical target volume in IDH1-wildtype glioblastoma is based on the ce-T1 MRI volume, as numerous studies have shown that survival is associated with both the extent of surgical resection and residual ce-T1 volume." (PMID 39061219, 2024). "For the <55-year age group, out of 18 cases of glioblastoma, six cases were categorized as glioblastoma, IDH1 mutant type, due to immunoreactivity for IDH1, and 12 cases were categorized as glioblastoma, NOS (not otherwise specified), due to IDH1 negativity." (PMID 39165459, 2024). "For instance, in a murine xenograft model of human glioblastoma, IDH1 silencing improved the response to fractionated radiotherapy via the reduction of NADPH, deoxynucleotides and glutathione, which usually help repair radiation-induced DNA damage." (PMID 39518074, 2024). "All cases of grade 4 astrocytoma were IDH1-positive, whereas all cases of glioblastoma were IDH1-negative." (PMID 39192927, 2024).
glioblastoma (continued). "IDH-1 mutant astrocytomas and oligodendrogliomas tend to be less aggressive than IDH-1 wildtype glioblastomas (GBs); however, IDH-1 mutant astrocytomas can still be classified as grade IV." (PMID 38672661, 2024). "We found that HMGB3 and YBX1 were predicted to target 11 risk genes for glioblastoma, including RPL5 and IDH1, as shared target genes." (PMID 39363111, 2024). "In astrocytoma, median OS was reported to vary between 5.8 months in elderly patients to 23.8 months in diffuse grade 4, IDH1/2 wildtype astrocytoma with molecular features of glioblastoma and to 5.2 years for low-grade astrocytoma." (PMID 38571509, 2024). "In 65% (26/40) of the cases, we observed IDH1 wild-type glioblastomas with sizes under 5 cm, while 25% (1/4) of the cases were IDH1 mutant glioblastomas larger than 5 cm." (PMID 39684754, 2024). "The most frequent histologies were ganglioglioma CNS WHO grade 1 (55 patients, 35.0%) and IDH1 wildtype glioblastoma (36 patients, 22.9%)." (PMID 39479007, 2024). "After vaccination, overall survival improved in the IDH1-wt/TERTp-mut glioblastoma group, which had the lowest B7-H4 expression among the other two groups." (PMID 38932383, 2024). "In this study, a TBR threshold value of 2 was determined as optimal for the delineation of IDH1-wildtype tumor tissue using [18F]-FACBC in patients with glioblastoma." (PMID 39061219, 2024). "In the study, 33/35 CNS WHO 4 brain cancers were diagnosed as glioblastoma (IDH1-wildtype) and two were classified as IDH1-mutant astrocytoma." (PMID 38835368, 2024). "Patients with an IDH1-mutant glioblastoma reportedly have a better OS than patients with IDH1-wild-type anaplastic astrocytomas, suggesting that IDH status is more prognostic than histologic grade." (PMID 38406061, 2024). "The combination of IDH1-mut and MGMTp-met status is a more accurate predictor of survival in glioblastoma compared to either IDH1 or MGMT alone." (PMID 38893240, 2024). "The majority of IDH-1 wild-type glioblastomas (57.5%, 23/40) exhibited MMP-9 immunoexpression, in contrast to IDH1 mutant glioblastomas, where MMP-9 immunoexpression was significantly lower (1/4)." (PMID 39684754, 2024). "Equally important to the biomarker IDH1 mutation is MGMT gene silencing by methylation, which is found in about 50% of all newly diagnosed glioblastoma." (PMID 39767640, 2024). "In concordance with molecular observations, MF and MC glioblastoma are similar to IDH1/2 wt glioblastoma with SL and fit into the expected age of diagnosis." (PMID 39560695, 2024). "Almost all are glioblastomas according to the most recent, revised 2021 WHO classification of CNS tumours but one case needed to be reclassified because it carries an IDH1 mutation (R132H)." (PMID 38398141, 2024). "On the other hand, it has been shown that in isocitrate dehydrogenase 1 (IDH1) mutant cells such as glioblastomas, the oncometabolite, 2-Hydroxyglutarate, increases erastin-induced lipid ROS accumulation and sensitizes cells to ferroptosis." (PMID 38388563, 2024). "Most IDH1-mutant GBMs (92%) exhibit a proneural expression signature, indicating that secondary glioblastomas are relatively homogeneous, while primary glioblastomas are more heterogeneous with various expression profiles." (PMID 39767571, 2024). "This technique utilizes specific antibodies to detect and visualize the expression of proteins associated with glioblastoma, such as GFAP (glial fibrillary acidic protein), Ki-67, and IDH1 (isocitrate dehydrogenase 1)." (PMID 39338377, 2024). "It concerned, among others, IDH1 status where samples of two of our patients carried IDH1mt variant, which has been previously suggested as the potential explanation of LTS in glioblastoma patients." (PMID 38654280, 2024). "At the optimal threshold value TBR > 2, [18F]-FACBC uptake was excellent for discriminating IDH1-wildtype tumor tissue, synonymous with glioblastoma in this patient cohort." (PMID 39061219, 2024).
glioblastoma (continued). "Mutations in IDH1 or IDH2 are positive prognostic factors, improving the prognosis of the patients when compared to IDH-wildtype glioblastomas." (PMID 38674436, 2024). "We assessed the model predictions from setup 1 for differentiating favorable from unfavorable prognosis in the important subgroups of IDH1 wild-type glioblastoma patients ≤70 and >70 years of age to evaluate the model predictions for treatment selection." (PMID 39156618, 2024). "Immunohistochemistry (IHC) for IDH1 was performed on 19 patients (61%), reporting positive results in 4/10 glioblastomas (40%), 3/4 anaplastic astrocytoma (75%), and in 5/5 oligodendroglial tumors (100%)." (PMID 39767683, 2024). "IDH1-wildtype glioblastoma multiforme (IDHwt-GBM) is a highly heterogeneous and aggressive brain tumour characterised by a dismal prognosis and significant challenges in accurately predicting patient outcomes." (PMID 38890658, 2024). "Associations between GRP78 or IGFBP‐2 IHC protein expression and clinicopathological features of IDH1‐wildtype glioblastoma (n = 92)." (PMID 37212470, 2023). "IDH1 and IDH2 mutations have been described in different types of cancer, including glioblastoma, and are being targeted for acute myeloid leukaemia." (PMID 36880517, 2023). "Compared to IDH1-mutant tumours, glioblastomas showed significantly higher expression of EGFR, MEOX2, and CD34 and significantly lower positivity for SOX11." (PMID 37568909, 2023). "Mutations in isocitrate dehydrogenase 1 (IDH1) and isocitrate dehydrogenase 2 (IDH2) are associated with improved survival rates among patients with glioblastoma and are positive prognostic predictors of overall survival." (PMID 38173841, 2023). "Thirty-seven tumors were IDH1-wildtype (36 glioblastomas, 1 anaplastic astrocytoma (2016), or glioblastoma (2021), 13 tumors were IDH1-mutant (1 glioblastoma (2016), or astrocytoma, grade IV (2021), 5 anaplastic astrocytomas, 7 anaplastic oligodendrogliomas)." (PMID 37345097, 2023). "In this study, we focused on the effect of IDH1 wild-type glioblastoma on the human hippocampus volume." (PMID 37178276, 2023). "We observed an adaptive response of the hippocampus, with an increased volumetric value more pronounced on the side contralateral to the lesion, in a cohort of adult IDH1 wild-type glioblastoma patients." (PMID 37178276, 2023). "Though the clinical data in this study was limited to a subset of patients with wild-type IDH-1 glioblastoma under α-PD-L1 treatment, the concurrent dexamethasone diminished the response to α-PD-1 therapy in two different mouse glioma models." (PMID 38239396, 2023). "As 96% of patients with primary glioblastoma contain wt IDH1 (as compared to only 27% of secondary glioblastoma), our study is only relevant to potential IL-11Rα-enhanced survival advantages in the primary glioblastoma context." (PMID 36834778, 2023). "To identify a gene signature to classify control subjects and patients with glioblastoma (i.e., IDH1 wild-type), we used 569 genes differentially expressed between the two groups as predictors of the diagnosis (0 = control, 1 = glioblastoma)." (PMID 37568598, 2023). "Due to stringent inclusion criteria, 15 patients affected by IDH1 wild type glioblastoma were included and compared to 19 age-matched controls." (PMID 37178276, 2023). "High expression of BCAT1 is a marker for predicting poor prognosis in IDH1 wild-type glioma patients, providing an important target site for glioblastoma patients." (PMID 38028625, 2023).
glioblastoma (continued). "In 2008, the discovery of somatic mutations that affect the active site of the Krebs cycle enzyme, IDH1, was initially observed during a comprehensive genomic analysis of tumor samples from human glioblastoma." (PMID 37881322, 2023). "This study made use of tissue from IDH1 wild type (IDH1-wt) glioblastoma (n = 18) and IDH1 mutant (IDH1-mt) astrocytoma (n = 12) tumors." (PMID 38168422, 2023). "In this real-world cohort, among the 18 patients who received targeted therapy, there were two patients with IDH1-mutant high-grade astrocytoma that were excluded from our analysis based on the WHO 2021 classification of glioblastoma." (PMID 38143440, 2023). "The inhibition of GLS by BPTES in glioblastoma cells decreases glutamate, and α-KG levels, and reduces the growth of mutant IDH1 cells compared to those expressing wild-type IDH1." (PMID 38139462, 2023). "In IDH1 wildtype glioblastomas, the TME is more immunosuppressive, where Tregs and tumor-associated macrophages contribute to the release of immunosuppressive signals." (PMID 36644500, 2023). "The current DC-vaccination trial included 37 patients with a diagnosis of recurrent glioblastoma (IDH-1 wild type, n = 28, 76%) or grade 4 astrocytoma (IDH-1 mutated, n = 9, 24%)." (PMID 36831580, 2023). "We underline the fact that observations on a larger sample size are needed, but based on the analysis we conducted, we can reasonably candidate MsEVs and MsLVs as morphological biomarkers related to the Ki67 index in adult glioblastoma IDH1." (PMID 37509607, 2023). "In this study, we evaluate the correlation between PSMA and VEGF expression in a cohort of IDH1/2 wild-type glioblastomas and correlate it with known prognostic factors and outcomes." (PMID 37189766, 2023). "The immunological profile of the glioblastoma microenvironment differs between wildtype and IDH1 mutant forms." (PMID 36644500, 2023). "From this analysis, we found ten DEGs specific to IDH1-wt glioblastoma, namely, S100A11, AC091932.2, PIGH, AC020910.5, RPS8P6, AC105339.6, AL589986.1, AL049874.3, CEBPD, and Z99496.1." (PMID 37568598, 2023). "IDH1-wildtype glioblastoma has a poorer prognosis than the IDH1-mutant astrocytoma which shows higher PMI values." (PMID 36653382, 2023). "Similar results were obtained by Kaplan–Meier analysis, t-ROC, and DCA assessment of IDH1-WT glioblastoma based on CXCR4 in PRSM." (PMID 37626511, 2023). "Univariate Kaplan–Meier and Cox proportional hazards of associations between OS, and combinations of IGFBP‐2/GRP78 IHC protein expression of IDH1‐wildtype glioblastoma (n = 92)." (PMID 37212470, 2023). "Among 80 percent of LGGs and secondary glioblastoma accompanied with IDH1-mut character are usually younger than people with IDH1-wt." (PMID 37029174, 2023). "All patients were diagnosed with isocitrate-dehydrogenase-1 (IDH-1) wild type and diagnosed positive for Glioblastoma multiforme." (PMID 36901897, 2023). "In the TCGA set, patients with higher risk score tend to be older than 40 years, to have higher WHO grade, unmethylated MGMT promoter, glioblastoma, non‐codeletion of 1p/19q and wild type IDH1 (all p < 0.001)." (PMID 36856182, 2023). "In low-grade glioblastoma (LGG), more than 80% of IDH mutations occur in the IDH1 gene, being dominated by R132H IDH197." (PMID 36778129, 2023). "SNX10 expression strongly correlated with IDH1 status, tumor histology, and tumor grade; SNX10 expression was higher in patients with wild-type IDH1 and glioblastoma patients." (PMID 36795488, 2023). "The most common and aggressive glioma is IDH1/2 wild-type glioblastoma, with a median overall survival of 14 months." (PMID 37189766, 2023). "Eight genes, AC016737.2, BNC2-AS1, AC007040.1, AC009248.3, SOCAR, LAGE3, TOMM20L, and FP671120.11, were specific to patients with IDH1-wt and TERT-promoter-mutated glioblastoma." (PMID 37568598, 2023).
glioblastoma (continued). "Clinicopathological variables and covariates for 9 patients with a high IGFBP‐2/low GRP78 IHC protein expression in a cohort of 92 patients with IDH1‐wildtype glioblastoma." (PMID 37212470, 2023). "Two genes, AC017104.4 and UNC93B7, were found to be specific for patients with IDH1-wt, TERT-promoter-mutated, and MGMT-methylated glioblastoma." (PMID 37568598, 2023). "The ultrastructural analysis presented in this study provides valuable insights into lipid accumulation and distribution within IDH1-wt glioblastoma and IDH1-mt astrocytoma tumors as well as their implications on tumor survival and aggressiveness." (PMID 38168422, 2023). "Univariate Kaplan Meier and Cox proportional hazards analysis of associations between OS, clinical covariates and GRP78/ IGFBP‐2 IHC protein expression of IDH1‐wildtype glioblastoma (n = 92)." (PMID 37212470, 2023). "When compared to traditional molecular prognostic markers, such as IDH1 mutation, the NLR can appropriately assess the prognosis in glioblastoma (GBM) patients in order to guide therapeutic decisions and patient management." (PMID 38003396, 2023). "The role of each of the highly expressed HDAC enzymes was molecularly dissected using lentiviral RNA interference knock-down vectors and a patient-derived IDH1 mutant in vitro model of glioblastoma (HK252)." (PMID 37528157, 2023). "Mutations in IDH1 and 2 are the fundamental hallmarks of brain cancers and they are reported up to ≥80% in WHO grade II/III astrocytomas, oligodendrogliomas, glioblastomas, and oligoastrocytomas." (PMID 36903561, 2023). "Molecular profiles similarly indicated a poor-risk biological cohort including predominance of IDH-1 wild type (85.7%), MGMT unmethylated (57.1%) tumors with EGFR, PTEN, and CDKN2A profiles in keeping with molecular glioblastoma." (PMID 36402744, 2023). "Additionally, the co‐deletion of 1p/19q and IDH1/2 mutations in patients with low‐grade glioma indicate a better clinical prognosis; however, the effect of these molecular events in glioblastoma (GBM) is unclear." (PMID 34953037, 2022). "Increased glutamate tissue levels in IDH1-WT glioblastoma correlated with several gene expression changes, indicating different roles of glutamate in multiple metabolic pathways." (PMID 34941573, 2022). "MRT demonstrated a typical ring-shaped gadolinium enhancement in the left frontal lobe with typical ring gadolinium enhancement, after which subtotal removal of an IDH1/2 wild-type glioblastoma was performed." (PMID 35992802, 2022). "Between 2013 and 2018, 175 IDH1 wild-type glioblastoma (GB) patients underwent 5-ALA guided surgery." (PMID 35565263, 2022). "The mutation rate of IDH1 (R132H) in LGG was 77.57%, and the mutation rate in glioblastoma was 6.45%." (PMID 35982398, 2022). "IDH1/2 mutant tumors such as glioblastomas, chondrosarcomas, and gastric cancers have also been shown to be more sensitive to NAMPT inhibition." (PMID 35814452, 2022). "Another finding included decreased levels of butyrate, a neuroprotective gut metabolite, in both IDH1-mut and IDH1-WT glioblastoma, suggesting further investigations on the role of microbial metabolites." (PMID 34941573, 2022). "There was one pilocytic astrocytoma, nine astrocytomas with IDH1-mutant, 10 astrocytomas with IDH1-wildtype, four oligodendrogliomas, NOS, and 18 glioblastomas with IDH1-wildtype." (PMID 35204029, 2022). "Mutations in IDH1 and IDH2 genes were initially identified by exome sequencing of colon cancer and glioblastoma cells." (PMID 35741254, 2022). "Genomic alterations like IDH1/2 mutation, EGFR amplification and chromosomal 1p/19q deletions have been characterized in glioblastoma pathogenesis, molecular subtyping as well as treatment response." (PMID 35183197, 2022).